INS (insulin)
Diseases named in the same sentence as INS in open-access papers (continued):
Sharing a sentence is not in itself a finding about the gene and the disease.
Hypoglycemia (continued). "This new ultra-long insulin analogue presents as advantages flexibility in dose timing and lower risk of hypoglycemia." (PMID 26136850, 2015). "Postprandial HH (PPHH) is a condition that causes hypoglycaemia within a few hours of meal ingestion due to inappropriate insulin secretion in response to the meal." (PMID 26316429, 2015). "The differential pIR activities associated with the insulin and Cmpd1 combination in liver vs. peripheral tissues (i.e. higher insulin tone in liver vs. muscle) mimics endogenous insulin tissue actions, potentially contributing to reduced hypoglycemia risk." (PMID 25799496, 2015). "It is important that physicians not only consider the daily quantity or type of insulin, but should also intervene in the modifiable factors that affect hypoglycemia among patients who are at high risk for future hypoglycemic incidents." (PMID 26102197, 2015). "Dapagliflozin is an orally available SGLT2 inhibitor with an insulin independent mechanism of action and a lower risk of hypoglycemia than with conventional antidiabetic agents such as sulfonylureas and insulin." (PMID 26474563, 2015). "Immunological hypoglycemia associated with insulin antibodies (IAbs) induced by exogenous insulin was first reported by Harwood in 1960." (PMID 25961056, 2015). "Long-acting insulin analogs (LAAs) have been developed by modification of insulin chain in order to improve pharmacokinetic properties and decrease the risk of hypoglycemia." (PMID 25585592, 2015). "Hypoglycemia in an elderly patient with non-Hodgkin’s lymphoma was associated with normal insulin and insulin-like hormone levels but high TNF-α levels." (PMID 26284064, 2015). "From a CL perspective, this facilitates safer operation of CL by avoiding hypoglycemia resulting from sensor over-reading, whereas this risk is mitigated in the hypoglycemia range as insulin delivery is suspended by the algorithm." (PMID 26241693, 2015). "As in sepsis, dysregulation of the cortisol, insulin, mitochondrial, or other metabolic pathways have been implicated in the aetiology of hypoglycaemia and deserve further investigation." (PMID 25858094, 2015). "Intense insulin therapy (to achieve euglycemia) has been associated with increased mortality and hypoglycemia when compared with moderate glucose control." (PMID 26253538, 2015). "They carry a low risk of hypoglycemia, which is particularly important in the inpatient setting where changes in oral intake, insulin timing, and comorbid conditions such as acute kidney injury can put patients at risk." (PMID 28702223, 2015). "The action of SGLT2 inhibitors is glucose-dependent, becoming negligible when plasma glucose concentration drops below 90/mg/dL, so the risk of hypoglycemia is lower than with insulin-dependent antidiabetic drugs." (PMID 26474563, 2015). "By augmenting the glucose stimulated increase in plasma insulin, 55P0110 thus shows distinct anti-hyperglycaemic action in combination with low risk for fasting hypoglycaemia in mice." (PMID 25973898, 2015). "Hyperinsulinaemic hypoglycaemia (HH), one of the most frequent causes of persistent hypoglycaemia in neonates and infants, is a heterogeneous condition caused by dysregulation of insulin secretion from pancreatic β-cells." (PMID 26316429, 2015). "In ectothermic toads, for instance, induction of hypoglycemia via both insulin and 2-deoxyglucose is associated with a behavioral drift towards lower temperatures." (PMID 30873441, 2015). "In these cases the use of SGLT2 inhibitors resulted not only in better glycemic control in most patients but also in some patients' less hypoglycemia, weight loss, and decreased doses of insulin." (PMID 25785209, 2015). "Intensive insulin therapy was associated with a higher risk of severe hypoglycemia in this study, and this finding is in agreement with previous reports." (PMID 26102197, 2015).
Hypoglycemia (continued). "In the present study, we found that assistance from family members at the time of insulin injection was associated with a reduced risk for both mild and severe hypoglycemia, after adjustment for intensive insulin therapy." (PMID 26102197, 2015). "The existing oral antidiabetics demonstrate severe side-effects, and treatment with insulin increases the risk of weight gain and hypoglycemia." (PMID 25574213, 2015). "These agents have a relatively low risk of hypoglycemia, favorable short-term side effect profile, and can be used alone or in combination with insulin." (PMID 28702223, 2015). "Because the effects of GLP-1 on insulin secretion are glucose-dependent, the risk of hypoglycemia associated with DPP4 inhibitor treatment is low." (PMID 26021829, 2015). "Serum insulin and C-peptide levels confirmed marked endogenous hyperinsulinemia as the cause of the severe hypoglycemia." (PMID 25692049, 2015). "Hypoglycemia is the major downside of sulfonylurea or insulin-based regimens and is one of the major causes of hospitalisations with T2DM as main diagnosis in our study." (PMID 25645749, 2015). "Although exenatide infusion was associated with varied frequency of hypoglycemia (0.1–10 %), this was significantly lower than with insulin." (PMID 28702223, 2015). "In these studies, a higher prevalence of hypoglycemia was associated with intensive insulin therapy." (PMID 25888011, 2015). "Treatment with continuous s.c. insulin infusion (CSII) provides better glycemic control and lower risk of hypoglycemia than conventional therapy with multiple daily insulin injections." (PMID 25614824, 2015). "In cases that are assumed to be healthy, the most frequent causes of hypoglycemia are drugs, insulinoma, islet cell hyperplasia/nesidioblastosis, and factitious hypoglycemia due to surreptitious administration of insulin or sulfonylureas." (PMID 26558131, 2015). "The two treatments have synergistic mechanistic actions and the results of clinical trials show that the combination of DPP-4 inhibition and insulin improves glycemia with low risk of hypoglycemia and prevention of weight gain." (PMID 26587020, 2015). "Although factitious insulin use is one of the most important causes in the differential diagnosis of hypoglycemia in diabetic patients, it frequently remains overlooked." (PMID 25541899, 2014). "There was no exposure history to insulin or insulin-stimulating drug therapy; therefore, oral hypoglycemic agents or exogenous insulin-induced causes of hypoglycemia were excluded." (PMID 25289063, 2014). "During Ramadan fasting, the decrease in blood glucose levels triggers compensatory mechanisms in the body of healthy individuals which cause a reduction in insulin secretion or the breakdown of stored glycogen to prevent hypoglycemia." (PMID 25435876, 2014). "Critically ill patients often receive insulin infusion, although concerns with the risk of hypoglycemia and failure to show a positive impact on patient outcome has altered the frequency of use." (PMID 24598381, 2014). "In a meta-analysis, Monami and colleagues found that the use of glargine and detemir resulted in decreased hemoglobin A1c (HbA1c) and a reduced risk of nocturnal and severe hypoglycemia when compared to insulin NPH." (PMID 24653838, 2014). "In fact, patients with T1DM regularly compensate their glucose management by elevating pre‐exercise glucose concentrations through a reduction in insulin dosage to offset the risk of hypoglycemia." (PMID 25413321, 2014). "Postoperatively, glycemic control should be monitored closely, as the sudden withdrawal of catecholamines can increase insulin sensitivity and cause severe hypoglycaemia." (PMID 25110602, 2014). "Since insulin therapy employs either continuous insulin infusion or setting controlled glucose levels at low levels, there is an increased risk of hypoglycemia, thereby presenting methodological problems to these studies." (PMID 24747428, 2014).
Hypoglycemia (continued). "We found that the use of glyburide in GDM increases the risk of macrosomia and neonatal hypoglycemia in comparison to insulin." (PMID 25302493, 2014). "In type 1 diabetic subjects with GH deficiency, the daily insulin requirement can be reduced, and these patients are more prone to episodes of hypoglycemia." (PMID 24966876, 2014). "For these reasons, hypoglycemia associated with the administration of insulin and its potential as a trigger for brain damage and cognitive deficit in children will be covered more specifically in the next section of this review." (PMID 24790575, 2014). "Several barriers exist for the initiation and subsequent optimization of insulin therapy, including the risk of hypoglycemia, weight gain, and concerns about daily injections and/or restrictions to lifestyle." (PMID 24620742, 2014). "Abnormalities in laboratory results include hypoglycemia associated with elevated levels of insulin and high activity of C peptide, corresponding to the overproduction of endogenous insulin." (PMID 25202394, 2014). "Poor knowledge of the causes and prevention of the ketoacidosis, insulin reaction and hypoglycemia increases their risk of developing them, which will invariably lead to poor adherence to insulin therapy." (PMID 24397956, 2014). "The risk of incurring hypoglycemia, weight gain and adiposity -- on top of what is the result of GC therapy -- is a significant drawback of insulin treatment." (PMID 24423471, 2014). "Patients with type 1 or severe type 2 diabetes are at high risk of life-threatening hypoglycemia, due to a combination of intensive insulin treatment and impaired glucagon secretion." (PMID 24616659, 2014). "In agreement with previous studies, our meta-analysis demonstrated that intensive insulin therapy carries a markedly increased risk of hypoglycemia." (PMID 25136614, 2014). "The continued use of insulin at a glucose level below 5.6 mmol/l has recently been identified as one of the most common causes for hypoglycemia in an analysis of > 55,000 glucose readings in 1,657 patients." (PMID 25074071, 2014). "It was considered that hypoglycemia caused by the excess insulin leads to increased secretion of gluconeogenic hormones such as growth hormone and elevated gluconeogenesis." (PMID 24741073, 2014). "The relationship between insulin type and risk of hypoglycaemia during the study remained consistent in the sensitivity analyses." (PMID 25048824, 2014). "Antidiabetic agents such as insulin and sulphonylureas were associated with six cases of hypoglycemia in this study." (PMID 24475089, 2014). "Most of physicians are reluctant to continue to increase insulin doses or to carry out intensive insulin treatment due to the side effects associated with insulin-induced hypoglycemia and weight gain." (PMID 24650537, 2014). "Our results suggest that BOT using insulin glargine is an option of insulin therapy with 1% risk of hypoglycemia in patients with T2DM with inadequate glycemic control." (PMID 24528773, 2014). "After making adjustment for publication bias using the trim and fill method, risk for neonatal hypoglycemia still remained significantly higher with glyburide compared to insulin (RR, 1.95; 95% CI, 1.04–3.67)." (PMID 25302493, 2014). "In conclusion, our results suggest that BOT using insulin glargine is an option of insulin therapy with a 1% risk of hypoglycemia in insulin-naïve patients with T2DM with inadequate glycemic control." (PMID 24528773, 2014). "None of our patients developed hypoglycemia, which confirms that insulin treatment with moderate objectives reduces the risk of hypoglycemia." (PMID 24628829, 2014). "In a recent small series, hypoglycemia improvement after everolimus was associated with a reduction in serum insulin levels." (PMID 25298880, 2014). "Sik3−/− mice show reduced energy storage, which is associated with hypoglycaemia and hyper-insulin sensitivity." (PMID 25060954, 2014).
Hypoglycemia (continued). "As a consequence, the use of these agents is more frequently associated with hypoglycemia than with any other antidiabetic pharmacotherapy, except for insulin." (PMID 24524730, 2014). "Administering insulin after the surgery would increase the risk of hypoglycemia and taking more lung samples after the surgery would be unacceptable." (PMID 25278226, 2014). "Hypoglycemia, use of insulin, and use of sulfonylureas are associated with increased risk for major cardiovascular (CV) events, CV disease, and death." (PMID 25433668, 2014). "In particular, patients have difficulties increasing the insulin dose because they fear hypoglycemia and because they associate higher insulin doses with disease progression." (PMID 25340869, 2014). "Possible causative factors of recurrent hypoglycemia in the present case included insulin use, malnutrition, and severe infection resulting from the lung abscess." (PMID 24524438, 2014). "He defaulted from follow-up without therapy and some months later developed episodic severe hypoglycaemia, which was found to be associated with inappropriately elevated insulin and C-peptide levels." (PMID 24683485, 2014). "This low risk for hypoglycaemia can be regarded an advantage of this class of medicines as compared with classical antidiabetic compounds such as insulin or sulphonylureas." (PMID 25365416, 2014). "Although further efficacy and safety data are needed, because tofogliflozin acts independently from insulin, there is little risk of increasing the burden on the pancreas and causing hypoglycemia." (PMID 24678906, 2014). "Inusulinomas are β-cell-derived tumours that secrete insulin and can cause hyperinsulinism, potentially leading to both hypoglycemia and neuroglycopenic symptoms." (PMID 25006548, 2014). "The same authors demonstrated afterwards that insulin-induced hypoglycemia was associated with a significantly increase in CO2 chemosensitivity, an effect that was mediated by the CB, since the effect was lost in animals that had their CSN resected." (PMID 25400585, 2014). "In the absence of contraindications, metformin is preferred over other agents due to equal potency and a low risk of hypoglycemia, and also as it causes less weight gain compared with insulin secretagogues." (PMID 24427312, 2014). "TAK-875 is a selective GPR40 agonist that improves glycemic control in T2DM patients by potentiating postprandial insulin secretion in a glucose dependent manner with a minimal risk for hypoglycemia." (PMID 25374542, 2014). "The common causes of hypoglycemia in the diabetic patients were low calorie intake due to illness or dieting (23/33) and suspected overdose of insulin or oral anti‒diabetic agents (5/33)." (PMID 25520819, 2014). "Insulin therapy is probably the safest and most effective therapy in patients with liver dysfunction, with the limitation that increased risk of hypoglycemia in such patients requires extra care with insulin dosage." (PMID 23574917, 2013). "The continuation of metformin after insulin initiation has been associated not only with weight reduction, lower levels of A1C, and lower insulin requirements but also with a higher risk of hypoglycemia." (PMID 24011173, 2013). "Most subjects (96.3%) were on background AHA therapy associated with an increased risk of hypoglycaemia (i.e. insulin or sulphonylurea agents)." (PMID 23464594, 2013). "Hypoglycaemia-associated accidents are a well-appreciated concern for people receiving insulin therapy." (PMID 23121373, 2013). "Hyperinsulinism is an important cause of hypoglycemia and is biochemically characterized by unregulated insulin secretion from the pancreatic beta cells in relation to blood glucose concentration." (PMID 24072082, 2013). "Premixed insulins are, however, associated with an increased risk of daytime hypoglycaemia compared with basal insulin alone." (PMID 22998363, 2013).
Hypoglycemia (continued). "Further studies are clearly needed to determine which mechanism(s) underlie insulin-hypoglycemia-induced ROS production." (PMID 23894333, 2013). "IDet is suitable for use in ND children and adolescents, and those wanting to switch basal insulin to reduce the risk of hypoglycemia, especially nocturnal hypoglycemia." (PMID 23448369, 2013). "Controlling glycemia has proved difficult due to the associated risk of hypoglycemia when highly dynamic patients are treated with exogenous insulin." (PMID 23437328, 2013). "•DPP-4 inhibitors have a low risk of hypoglycemia due to their effect as glucose-dependent insulin secretagogue." (PMID 23697612, 2013). "But they also demonstrated that, although to a lesser extent,insulin-induced hypoglycaemia was associated with an increased risk for ICU death." (PMID 23510051, 2013). "Because the action of GLP-1 on insulin secretion is strictly glucose dependent, the risk of hypoglycemia associated with DPP IV inhibitors is low." (PMID 23621921, 2013). "Air travel also increases the risk of hypoglycemia, requiring adjustment of the dosage and timing of insulin administration." (PMID 24360506, 2013). "Although the DCCT was carried out before the availability of current insulin analogs, the risk for more frequent hypoglycemia should be considered when determining A1c targets for this age group." (PMID 24156395, 2013). "It is given to patients who are on insulin and causes a mild reduction in HbA1c and mild weight loss but is associated with nausea and hypoglycemia that requires the reduction of insulin dosing by as much as 50%." (PMID 24260037, 2013). "These include reduced risk of severe hypoglycaemia and weight gain compared to rapid-acting insulin, a mitigation of the weight gain associated with basal insulin therapy, and a reduced regimen complexity." (PMID 23061470, 2013). "With appropriate titration, insulin therapy is highly efficacious but is associated with hypoglycaemia." (PMID 23130654, 2013). "Similar to the finding by Van Roozendaal & Krass (2008), there was a potential risk of hypoglycemia in patients receiving oral antidiabetic drugs or insulin." (PMID 23289895, 2013). "In the present work, two particular clinical entities have been analysed whose pathologies are associated to the presence of high levels of insulin (auto)antibodies together with transient episodes of hypoglycemia." (PMID 24386337, 2013). "The post hoc analyses presented here indicate that saxagliptin used as an add-on to another non-insulin antihyperglycaemic agent (except perhaps a sulphonylurea) can achieve large decreases in HbA1c with minimal risk of hypoglycaemia." (PMID 23795975, 2013). "A major concern with antidiabetes treatments, particularly insulin and insulin secretagogues such as sulphonylureas or meglitinides, is the risk for iatrogenic hypoglycaemia." (PMID 23061470, 2013). "In the UKPDS 33 study, intensive treatment with sulfonylureas or insulin was associated with an increased incidence of hypoglycemia and weight gain." (PMID 23958390, 2013). "For instance, angina following an acute episode of hypoglycaemia was reported, and hypoglycaemia secondary to a massive insulin overdose produced ECG and enzyme changes associated with acute coronary syndromes." (PMID 24053606, 2013). "In vivo administration of ribose is associated with several risk factors such as hypoglycemia, enhanced insulin levels as well as formation of cross-linked protein aggregates (glycation reaction) which results in cellular dysfunction." (PMID 24066139, 2013). "The addition of a single prandial insulin injection at the largest meal is well tolerated and associated with significant improvements in glycated haemoglobin (HbA1c), low rates of hypoglycaemia and limited weight gain." (PMID 22998363, 2013). "Intraperitoneal insulin injection caused significant comparable hypoglycemia in the C and CCM Groups during the ITT." (PMID 24119413, 2013).